EGFR (epidermal growth factor receptor)
Diseases named in the same sentence as EGFR in open-access papers (continued):
Sharing a sentence is not in itself a finding about the gene and the disease.
lung cancer (continued). "Further studies demonstrated that higher expression level of HHLA2 in human lung cancer tissues significantly associated with EGFR mutation, higher intensities of TILs and PD-L1 status, suggesting an effective immunotherapy strategy for PD-L1-negative patients." (PMID 31015801, 2019). "In addition, BEZ235 enhanced the effect of the EGFR-targeting therapeutic BIBW2992 on lung cancer cells with acquired resistant to TKIs caused by expression of the EGFR-T790 M mutant." (PMID 31262325, 2019). "Thus our results clearly confirm the observation from previous studies that EGFR mutations are more prevalent than KRAS in Chinese lung cancer patients." (PMID 31369215, 2019). "IGFBP7 expression is highly associated with EGFR-TKI resistance in lung cancer cells." (PMID 30609749, 2019). "In the past ten years, big progress has been achieved in the treatment of LUAD with targeted lung cancer therapy such as drugs targeting the epidermal growth factor receptor (EGFR) mutation or the anaplastic lymphoma kinase (ALK)-rearranged NSCLC patients group." (PMID 31811110, 2019). "TTF-1 positivity could be a surrogate for EGFR mutations in driving oncogenicity in lung cancer patients." (PMID 31196060, 2019). "However, these treatments often lead to therapeutic resistance driven by mutations in the kinase domain, such as EGFR T790M, which confers Erlotinib (Tarceva) and Gefitinib (Iressa) resistance in lung cancers." (PMID 31215437, 2019). "In addition, we investigated the molecular effects of auranofin combined with osimertinib, an EGFR inhibitor used in EGFR-mutated lung cancer patients." (PMID 31660987, 2019). "Resveratrol and its derivatives have been found to exert some effects on EGFR‐TKI resistance in non‐small cell lung cancer (NSCLC), but the underlying mechanisms remain unclear." (PMID 30701693, 2019). "A de novo single-nucleotide mutation in the EGFR gene can cause the development of lung cancer." (PMID 31426517, 2019). "Liquid biopsies are FDA approved for lung cancer EGFR mutation tests as companion diagnostic." (PMID 31817988, 2019). "In patients with lung cancer, different methods have been used successfully to detect EGFR mutations from ctDNA, and studies have demonstrated that this approach was valuable for diagnosis, predicting treatment response, and monitoring acquired therapy resistance." (PMID 31185703, 2019). "TKI therapy might change the natural history of patients harboring an EGFR mutation, converting Del19 lung cancer from a disease with a poor prognosis to one with a more favorable prognosis." (PMID 31333456, 2019). "Indeed, a previous study has reported that the detection rate of EGFR mutations in plasma ctDNA from lung cancer patients was lower after chemotherapy or EGFR-TKI therapy." (PMID 31185703, 2019). "Further, Quintanal-Villalonga and his colleagues found that highly-expressed FGFR1 may result in a higher resistance to EGFR-TKI in the patients with EGFR-mutated lung cancer and those patients may benefit from combined EGFR/FGFR inhibition." (PMID 31998131, 2019). "Moreover, magnetic hyperthermia treatment by EGFR-targeted IONPs caused in major inhibition of lung tumor growth in in vivo orthotropic lung cancer model." (PMID 31035440, 2019). "The first ctDNA liquid biopsy approved for use in clinical settings was in lung cancer patients for the identification of EGFR mutations for first-line therapy or identifying resistance mutations that will allow for treatment with third generation EGFR inhibitors." (PMID 31488153, 2019). "In light of the fact that the majority of centres are probably still using PCR-based tests, it can be said that the IdyllaTM EGFR Mutation Test performs equally well as standard care tests for the majority of common and well-characterised lung cancer EGFR mutations." (PMID 30470932, 2019).
lung cancer (continued). "This case underscores the need to monitor mutational profiles in EGFR mutant lung cancer in parallel with the changes in drug regimens, which may help determine the appropriate subsequent treatment." (PMID 30625213, 2019). "First, for patients with EGFR mutations such as T790M in lung cancer, the efficacy of anti‐AREG may be restrained, as EGFR downstream signaling network remains active." (PMID 31493351, 2019). "Additionally, the AmoyDx Super-ARMS EGFR mutation test has been approved by the Chinese FDA for the detection of EGFR mutations in lung cancer." (PMID 31404988, 2019). "In the subgroup of inherited EGFR mutations, a secondary activating mutation occurred in 70.2% (33/47) of the germline EGFR mutation carrier lung cancer cases; similarly, in lung cancers diagnosed in germline T790 M mutation carriers, the proportion of a secondary activating mutation was 73%." (PMID 31703574, 2019). "In lung cancer that possessed oncogene addiction to the EGFR mutation, eventual development of resistance might be due to multiple mechanisms such as activation of the Ras pathway or generation of ROS involved." (PMID 31629402, 2019). "Potential genetic modifiers may contribute to somatic EGFR mutation in lung cancer, although current data is limited." (PMID 31703574, 2019). "Therefore, EGFR mutation detection is extremely valuable for the diagnosis and treatment of lung cancer." (PMID 31608233, 2019). "Additionally, low RHOB expression has been shown to correlate with a positive response to treatment with EGFR-tyrosine kinase inhibitors (EGFR-TKI) in EGFR-mutated lung cancer patients, and reversely high RHOB expression correlates with a poor response." (PMID 31200451, 2019). "Second- and third-generation EGFR inhibitors are being developed and tested for lung cancer patients and may be effective also for sinonasal tumour with EGFR exon 20 mutations." (PMID 29507386, 2018). "Some case reports also found that first-generation EGFR TKIs may be a desirable therapeutic strategy for patients with advanced lung cancer with synchronous 19Del and L858R mutations." (PMID 30055651, 2018). "The improvement in survival caused by EGFR‐TKIs in patients with an EGFR‐mutant lung cancer, and the propensity of these cancers to lead to a metastatic brain tumor, may contribute to this phenomenon." (PMID 30350450, 2018). "In addition, IGF1R is associated with the development of resistance to irreversible second-generation EGFR-TKIs in EGFR T790M-mutated lung cancer cell lines." (PMID 30445769, 2018). "This AI approach has been used in patients with somatic mutations in lung cancer to better classify the type of tumors using four large datasets and with focus on kRAS and epidermal growth factor receptor (EGFR), enabling a 75% prediction of mutations associated with these genes." (PMID 29695070, 2018). "Based on these findings, the authors have concluded that the polymorphism in exon 13 of the EGFR gene might be one of the molecular mechanisms of pleural metastasis of lung cancer." (PMID 30406002, 2018). "In other types of lung cancer with epidermal growth factor receptor (EGFR) mutations, commonly tyrosine kinase inhibitors (TKi) against the mutant EGFR or anti-EFGR antibodies are applied alone or in new combination therapy trials with other anti-cancer therapeutics." (PMID 29794999, 2018). "A deeper understanding of underlying molecular processes of EGFR signaling may provide insights into improving the management of EGFR-mutant lung cancer patients." (PMID 29455644, 2018). "On the other hand, we chose other lung cancer cell lines, H441 (wild-type EGFR), H3225 (L858R EGFR), H1975 (L858R, T790M EGFR), to test whether the mutations in EGFR could influence the afatinib labeling." (PMID 29765556, 2018). "The mutation rate of genes in the EGFR pathway are as high as 70–80% in lung cancer tissues." (PMID 30410721, 2018).
lung cancer (continued). "Some studies indicated that the irreversible EGFR TKI such as afatinib might be more effective for the patients with lung cancer harboring an uncommon mutation." (PMID 30428509, 2018). "More interestingly, the knockdown of SALL4 expression could suppress the migration, invasion, and metastasis of the lung cancer cells and significantly increase the sensitivity of EGFR mutated cells to Erlotinib." (PMID 29691367, 2018). "In addition, after reversible resistance to EGFR-TKIs in lung cancer cells, HGF can induce an irreversible second mutation." (PMID 29455668, 2018). "Notably, studies show that activated Akt signaling is involved in the therapeutic resistance of lung cancer, including both T790M and non-T790M mutation mechanisms of EGFR-TKIs resistance." (PMID 30382076, 2018). "Furthermore, we examined the role of NEDD4 in lung cancer H1650 cells that contain an EGFR deletion mutation, which is a common mutation that drives tumorigenesis and progression in lung cancer patients." (PMID 29455656, 2018). "In this study, we investigated the usefulness of ddPCR for quantitative detection of EGFR mutations in plasma samples and for guiding decisions regarding osimertinib therapy in lung cancer patients in a community setting who had developed resistance to first- or second-generation EGFR-TKI." (PMID 29963252, 2018). "Our preliminary study showed that radiomic features extracted from CT images might be promising biomarkers to predict EGFR mutations of lung cancer in vivo." (PMID 30547844, 2018). "For example, mutations in the EGFR protein kinase domain are found in 10–30% of lung adenocarcinomas, and treatment with tyrosine kinase inhibitors that specifically target the mutant protein kinase can produce temporary remissions in lung cancer patients." (PMID 29695735, 2018). "EGFR mutation and K-Ras mutation are regarded as mutation initiator in lung cancer patients." (PMID 29788985, 2018). "Furthermore, we examined the efficacy of EGFR-TKIs treatment in lung cancer patients with double mutation and single mutation in EGFR." (PMID 30172266, 2018). "Notably, EGFR tyrosine kinase inhibitors (TKIs) have become the standard first-line treatment for advanced lung cancer patients with activating EGFR mutations." (PMID 30382076, 2018). "The knockdown of HER2 restored sensitivity to EGFR TKIs in H1781 lung cancer cells which have the G776YVMA mutation, suggesting that inhibition of HER2 may prove a promising target to bypass EGFR TKI resistance." (PMID 29973561, 2018). "Patients with lung cancer harboring a “single sensitizing uncommon mutation”, including G719X, S768I, and L861Q, usually had a good treatment response to EGFR TKI, although the response was generally still inferior to those harboring common sensitizing mutations." (PMID 30428509, 2018). "Indeed, DUSP6 downregulation has been implicated in resistance to EGFR-targeted therapy in lung cancer." (PMID 29490281, 2018). "However, in other studies, induction of a Gas6-AXL pathway associated with EMT was shown to mediate EGFR TKI-induced resistance in lung cancer to cetuximab and erlotinib in HNSCC and to ALK inhibitors in ALKF1174L-positive human neuroblastoma cells." (PMID 29458371, 2018). "Therefore, further investigation is warranted to tease out the precise mechanisms of the internalization of mutated EGFR, which will assist the development of novel EGFR-targeted therapeutic strategy in the treatment of lung cancer." (PMID 29976202, 2018). "EGFR mutations are found in approximately 22% of all lung cancer metastases." (PMID 29435193, 2018). "Initial studies report that EGFR mutations could be detected in paired tumor and plasma samples in more than 70% of the patients with EGFR-mutant lung cancer." (PMID 29930751, 2018). "A deeper understanding of underlying molecular processes of EGFR signaling involving miRNAs may provide insights into improving the management of EGFR-mutant lung cancer patients treated with TKIs." (PMID 29455644, 2018).
lung cancer (continued). "Moreover, the frequency of CD39+CD8+ TILs was higher in epidermal growth factor receptor (EGFR)-mutated lung cancers, a subgroup of patients showing low CD8+ T-cell densities and relatively poor responses to ICB." (PMID 30477280, 2018). "This might be explained by the fact that Asian female patients with lung cancer are more likely to have adenocarcinoma with EGFR mutation, making the disease biologically distinct and more effectively treatable with targeted therapy." (PMID 30646236, 2018). "In addition, EGFR-mutated lung cancer cells resistant to EGFR TKIs also harbor SMO amplification along with Met activation." (PMID 29581874, 2018). "This case suggests that gefitinib followed by osimertinib may be a safe and effective treatment option for patients with EGFR mutation–positive lung cancer who experience disabling cerebral infarction due to Trousseau syndrome." (PMID 30034636, 2018). "Moreover, it was reported that somatic mutations drive distinct imaging phenotypes in lung cancer and a radiomic signatures was able to successfully discriminate between EGFR+ and EGFR- cases." (PMID 30462705, 2018). "Despite the steric auto-inhibitory features, autonomous EGFR phosphorylation was observed in several cancer types including breast and lung cancer that either exhibit high EGFR surface concentrations through EGFR overexpression or bear oncogenic mutations favoring an active conformation." (PMID 30242154, 2018). "Analogous to the EGFR-activating mutations in lung cancer, identifying such addiction to the EGFR pathway in pancreatic cancer could lead to improved response to EGFR TKI treatment for selective pancreatic cancer patients." (PMID 30449278, 2018). "In conclusion, EGFR rs712829 and rs2072454 SNPs may be associated with lung cancer among Jordanians." (PMID 30011810, 2018). "Finally, Src-mediated MAPK signaling mitigates the anti-tumor activity of osimertinib in EGFR-TKI-sensitive lung cancer, and PIK3C2A mutations attenuate the effects of osimertinib in T790M-positive lung cancer." (PMID 29764505, 2018). "The observation that oncologists practicing in Boston are most likely to order lung cancer molecular tests was consistent with the fact that EGFR mutations conferring responsiveness to EGFR inhibitors were discovered in the Boston-based Harvard Comprehensive Cancer Centers." (PMID 29554880, 2018). "The results revealed that propolin C-regulated EMT molecule expressions might be through downregulation of PI3K/Akt and ERK signaling pathways in EGFR-mutated HCC827 lung cancer cells." (PMID 29681982, 2018). "The therapeutic methods targeting mutation-induced EGFR activation have exhibited great success in clinics for lung cancer patients harboring EGFR mutations, therefore, raising the opportunities to guide the targeted therapies for NSCLC patients who have the EGFR mutations." (PMID 30425968, 2018). "In this study, we prospectively investigate the efficacy and safety of osimertinib in elderly patients aged ≥75 years, with ineffective prior EGFR-TKI treatment or with recurrence of EGFR-TKI mutation-positive or T790M mutation-positive nonsmall-cell lung cancer." (PMID 29879078, 2018). "Furthermore, DT inhibited the proliferation of H146, H209 (small lung cancer cell line), and H1650 cells (lung adenocarcinoma cell line with EGFR mutation)." (PMID 29207614, 2017). "Previous studies have shown that loss of HDAC6 downregulates EGFR expression in lung cancer cells." (PMID 29113288, 2017).
lung cancer (continued). "In the most deadly cancer type – lung cancer, mutated EGFR was revealed as a major tumor driver." (PMID 29029422, 2017). "To further improve the EGFR‐TKI management strategy for lung tumors harboring EGFR mutations, we established a combination therapy that includes EGFR‐TKIs and an antivascular endothelial growth factor (VEGF) antibody, bevacizumab, to treat lung cancer tumors harboring EGFR T790M mutations in vivo." (PMID 28388009, 2017). "Additionally, we aimed to explore dynamic changes in EGFR mutation profiles and the appearance of acquired resistance during EGFR-TKI in EGFR mutated lung cancer patients." (PMID 29029416, 2017). "However, gefitinib particularly targets mutatant EGFR in lung cancer, and suppresses EGF-triggered and HER3-mediated Akt activation in chemoresistant cells." (PMID 28938696, 2017). "Taken together, we conclude that the triplet therapy may induce deep remission in lung cancer cells with EGFR T790M mutations in vivo." (PMID 28388009, 2017). "However, this retesting study also demonstrates less than full concordance between the RT-PCR and MS tests for detecting EGFR gene mutations in lung cancer patients." (PMID 29254176, 2017). "Our findings provide an important insight showing that EMT inhibitors may sensitize lung cancer cells to TKIs and prolong the efficacy of TKIs in lung cancer patients who carry EGFR mutations." (PMID 28683123, 2017). "Our results may also provide for a possible explanation for lower efficacy of current immunotherapies in lung cancer patients with an EGFR mutation." (PMID 29119113, 2017). "The MAPK signaling activation in the carcinogenesis of invasive bladder transition cell carcinomas has been addressed by a meta-analysis study, whereas the PI3K/Akt pathway is implicated as the target of miR-30a to overcome EGFR inhibitor resistance in lung cancer." (PMID 28829370, 2017). "A new research revealed that intra-tumoral neutrophils are related to EGFR mutation in lung cancer, so whether similar clinical association existed in our study?" (PMID 29207617, 2017). "This also includes matching those lung cancer patients who may have acquired the EGFR T790M mutation conferring resistance while on prior therapy with EGFR small molecule inhibitors and prescribing new generation of targeted therapies to help override this." (PMID 28256603, 2017). "In the metastatic setting, several EGFR TKIs (erlotinib, gefitinib, afatinib) prolong progression-free survival as compared with platinum based chemotherapy doublets in patients with EGFR mutated lung cancer." (PMID 27764781, 2017). "CNVs of different genes have been associated with resistance in EGFR mutant lung cancer." (PMID 28854272, 2017). "EGFR mutations seem to play a major role in breast and lung cancers." (PMID 29088782, 2017). "In lung cancer, it has been shown to be more effective in patients with EGFR mutation." (PMID 28399187, 2017). "In addition, a new future direction must be refocusing on several gene target therapies, mainly on pharmaceutical EGFR-TKIs compounds, widely applied in lung cancer, currently the leading cause of death by malignant diseases." (PMID 28904641, 2017). "The triplet therapy may have the potential to induce deep remission and prolong survival in patients with lung cancers harboring EGFR mutations." (PMID 28388009, 2017). "We thank Drs Jeffrey A. Engelman and Matthew N. Niederest at Massachusetts General Hospital Cancer Center for providing EGFR-mutated lung cancer cell lines, and Mr K. Miyata and Mr H. Ogura at Japanese Foundation for Cancer Research (JFCR) for help with the in vivo experiments." (PMID 28287083, 2017). "However, the molecular mechanisms underlying this lower efficacy of immunotherapies in EGFR mutant lung cancers are still unclear." (PMID 29119113, 2017). "Additionally, changes in EGFR have been associated with lung cancer, and this gene has been recommended as a drug target." (PMID 28178311, 2017).